PMS2 (PMS1 homolog 2, mismatch repair system component)
Diseases named in the same sentence as PMS2 in open-access papers (continued):
Sharing a sentence is not in itself a finding about the gene and the disease.
Lynch syndrome (continued). "Although a germline VUS in PMS2 was detected in this case, its clinical significance remains unclear and cannot serve as a basis for diagnosing Lynch syndrome." (PMID 41278281, 2025).
Lynch syndrome (continued). "The most recent MMR gene to be connected to Lynch Syndrome is PMS2." (PMID 37732318, 2023). "Therefore, in the medical care for colorectal cancer, if the dMMR testing result shows MSI-H or the loss of MLH1/PMS2 expression, checking for the BRAF V600E mutation helps distinguish Lynch syndrome-related colorectal cancers from sporadic ones." (PMID 37599324, 2023).
Lynch syndrome (continued). "Due to a germline mutation in the PMS2 gene, Lynch syndrome was diagnosed despite no family history of the tumor." (PMID 36620543, 2022). "This patient was a 48-year-old man with intestinal GC without previous cancer family history; the tumor showed loss of protein expression of MLH1 and PMS2 and the germline genetic analysis rule out a mutation in Lynch syndrome associated genes." (PMID 33525650, 2021). "Ovarian cancer does not occur in Lynch syndrome before the age of 40, and the PMS2 pathogenic variant only shows a 3% incidence at the age of 60–75." (PMID 34118983, 2021). "However, caution is needed, because it has been reported that the BRAF V600E mutation was detected in some colorectal cancers that developed in patients with Lynch syndrome attributable to the PMS2 gene." (PMID 31286289, 2020). "Based on the fact both MLH1 and PMS2 are negative in her metastatic lymph node tumor, this metastatic tumor must be associated with the Lynch syndrome." (PMID 31139268, 2019). "Until recently, no prediction models for Lynch syndrome (LS) had been validated for PMS2 mutation carriers." (PMID 28933000, 2018). "However, some reports showed cases with germline mutations among Lynch syndrome patients with colorectal cancer in which although MLH1 and PMS2 proteins were lost by IHC in cancer tissues, MLH1 promoter hypermethylation was observed." (PMID 29783979, 2018).
Lynch syndrome (continued). "In this study, we performed genetic analysis of peripheral blood from this endometrial cancer patient with MLH1 and PMS2 protein losses using IHC despite MLH1 promoter hypermethylation because Lynch syndrome was suspected based on family history and clinical factors." (PMID 29783979, 2018). "Together, the contributions described herein may advance understanding of PMS2 and facilitate routine screening for Lynch syndrome in HCS offerings." (PMID 30268105, 2018). "In fact, presence of the BRAF V600E mutation in CRC essentially excludes Lynch syndrome, with the exception of rare cases associated with PMS2 germline mutation." (PMID 26875156, 2016). "However, this study was limited by our inability to test other MMR gene germline mutations associated with Lynch syndrome, including MSH6, PMS2, and EPCAM germline mutations." (PMID 27907203, 2016). "In addition, this study was limited by our inability to test for other MMR gene germline mutations that are also associated with Lynch syndrome, such as MSH6, PMS2 and EPCAM germline mutations." (PMID 26053027, 2015).
Lynch syndrome (continued). "It should also be noted that the majority of our patients carried MSH6 and PMS2 variants and thus may not be representative of all Lynch syndrome cohorts." (PMID 37078003, 2022). "The very high population frequencies of variants in MSH6 and PMS2 without typical Lynch syndrome associated cancers may ironically have falsely elevated the odds ratio." (PMID 34439310, 2021). "Therefore, the co-presence of the two alterations, the complexity of the familial history and the fact that PMS2 has a much lower penetrance for Lynch Syndrome than the other MMR genes, prevents us from assessing whether it is deleterious or not." (PMID 33821390, 2021).